THPO (thrombopoietin)
Diseases named in the same sentence as THPO in open-access papers (continued):
Sharing a sentence is not in itself a finding about the gene and the disease.
Crohn disease (1 paper, 2010). A gastrointestinal disorder characterized by chronic inflammation involving all layers of the intestinal wall, noncaseating granulomas affecting the intestinal wall and regional lymph nodes, and transmural fibrosis. "In human medicine, high plasma thrombopoietin concentrations were found in patients with ulcerative colitis and Crohn's disease, and both the procoagulant state and microvascular thrombosis may play a role in the pathogenesis of IBD." (PMID 20798868, 2010).
cytomegalovirus retinitis (1 paper, 2022). Infection of the retina by cytomegalovirus characterized by retinal necrosis, hemorrhage, vessel sheathing, and retinal edema. "We recommend that the platelet count be closely monitored and thrombopoietin be properly applied during the period when cytomegalovirus retinitis is prone to occur." (PMID 35372094, 2022).
dementia (1 paper, 2023). Loss of intellectual abilities interfering with an individual's social and occupational functions. "THPO, an activating cytokine, has been proposed to act early in dementia, and insulin-like growth factor binding protein-2 (IGFBP2) plays a modifying role." (PMID 37759795, 2023).
depression (1 paper, 2020). "In the In a mouse model of depression, repeated Arctigenin treatment shows antidepressant- and anxiolytic-like effects via promoting the expressions of angiogenin (ANG), thrombopoietin (TPO), and vascular endothelial growth factor (VEGF)." (PMID 33574759, 2020).
gastric adenocarcinoma (1 paper, 2024). "Overexpression of THPO in gastric adenocarcinoma tumor tissues has been reported, and its high expression leads to poor prognosis." (PMID 38228846, 2024).
gastric cancer (1 paper, 2025). A primary or metastatic malignant neoplasm involving the stomach. "While our study highlights the significant role of THPO in gastric cancer progression and its association with poor prognosis, several limitations must be acknowledged." (PMID 41049174, 2025). "We found that molecules such as ABCA6, DCLK1, and ADCYAP1 were linked to higher risk, with DCLK1 and ADCYAP1 being downregulated, while THPO and C5orf46 were upregulated in gastric cancer tissues." (PMID 41049174, 2025). "THPO, found to be upregulated in gastric cancer, was associated with advanced N stages." (PMID 41049174, 2025). "It was found that molecules like DCLK1 and ADCYAP1 were downregulated, whereas THPO and C5orf46 were upregulated in gastric cancer." (PMID 41049174, 2025). "A prognostic model constructed based on THPO and related molecules effectively predicted 1-, 3-, and 5-year survival rates for gastric cancer patients." (PMID 41049174, 2025). "In gastric cancer, we found that THPO was upregulated in tumor tissues, correlating with advanced disease stages and poorer prognostic outcomes." (PMID 41049174, 2025). "Subsequently, we investigated the biological role of THPO in the gastric cancer cell line MKN-45." (PMID 41049174, 2025). "THPO's positive correlation with M2 macrophages in gastric cancer suggests that it may influence the recruitment or differentiation of these cells, thereby contributing to an immunosuppressive microenvironment favorable for tumor progression." (PMID 41049174, 2025). "This relationship highlights the dual role of THPO in both promoting tumorigenic pathways and modulating the immune landscape, making it a potentially valuable target for therapies aimed at altering the immune response to gastric cancer." (PMID 41049174, 2025). "Furthermore, THPO knockdown in MKN-45 cells suppressed migration and blunted the EMT pathway, confirming its prometastatic role in gastric cancer." (PMID 41049174, 2025).
Insulin resistance (1 paper, 2022). Increased resistance towards insulin, that is, diminished effectiveness of insulin in reducing blood glucose levels. "Insulin resistance has also been shown to increase platelet count through an increase in thrombopoietin production by excess adipose tissue." (PMID 35453642, 2022).
liver cancer (1 paper, 2021). An epithelial or non-epithelial malignant neoplasm that arises from the liver. "Positive cross-regulation occurred with the alternative administration of siRNAs targeting THPO and those targeting VEGF-A in hypoxic liver cancer cell lines." (PMID 33673041, 2021). "Moreover, established liver cancer cell lines Huh7, HepG2, and Hep3B express functionally active THPOR, and interaction with recombinant THPO generates cell migration and chemoinvasion." (PMID 33673041, 2021).
megakaryoblastic leukemia (1 paper, 2018). "We investigated the consequences of p.R119C on the THPO function using the UT7‐TPO human megakaryoblastic leukemia cells, an engineered line stably expressing MPL that completely depends on THPO for growth and survival." (PMID 29191945, 2018).
migraine (1 paper, 2017). "The correlations of VEGF, angiopoietin-2 and thrombopoietin with the age of first ever migraine attack suggest that depletion of proangiogenic factors progresses with the duration of migraine." (PMID 28918499, 2017). "Age of migraine onset correlated with VEGF, angiopoietin-2 and thrombopoietin concentrations." (PMID 28918499, 2017).
multiple myeloma (1 paper, 2021). "This study aimed to evaluate the efficacy and safety of recombinant human thrombopoietin (rhTPO) for hematopoietic reconstitution after autologous stem cell transplant (ASCT) in patients with newly diagnosed multiple myeloma (NDMM)." (PMID 34569193, 2021).
neuroblastoma (1 paper, 2014). Neuroblastoma (NB) is the most common solid, extracranial childhood tumor. "Cytokines selected from primary, secondary, and tertiary clusters with respect to EPO (IL-11, KITLG, LIF, THPO) were chosen as experimental candidates, to test their effect on Egr2 mRNA expression in serum-starved EPOR-B104 neuroblastoma cells exactly." (PMID 24672526, 2014).
Opportunistic infection (1 paper, 2025). An infection that is caused by a pathogen that would generally not be able to cause an infection in a host with a normal immune system. "It explores the multifactorial pathophysiology, including direct viral effects on the bone marrow, drug-induced cytopenias, opportunistic infections, nutritional deficiencies, and CHF-related impairments in erythropoietin and thrombopoietin production." (PMID 40901202, 2025).
platelet disorders (1 paper, 2026). "Romiplostim, a fusion protein analog of thrombopoietin and eltrombopag, a thrombopoietin receptor agonist, are both FDA approved for the treatment or prevention of various platelet disorders and may be effective in this role." (PMID 41507122, 2026).
Stroke (1 paper, 2023). Sudden impairment of blood flow to a part of the brain due to occlusion or rupture of an artery to the brain. "In our study poor 90d outcomes were associated with enrichment of Thrombin pathways at 5 h and 24 h, Thrombopoietin Signaling at 5 h and the Intrinsic Prothrombin Activation Pathway at 24 h after stroke." (PMID 36691064, 2023).
type 1 diabetes mellitus (1 paper, 2021). A chronic condition characterized by minimal or absent production of insulin by the pancreas. "Moreover, plasma of type 1 diabetic patients exerted in vitro a priming activity on platelet–leukocyte interaction that appeared to be mediated by plasma THPO contents." (PMID 34210000, 2021).
type 2 thrombocytopenia (1 paper, 2013). "In several cell lines, PaCS development follows cell differentiation/activation by trophic factors and cytokines, such as GM-CSF and IL-4 for DCs, IL-2 and IL-15 for NK cells, or thrombopoietin, IL-6 and IL-11 for megakaryocytes in type 2 thrombocytopenia." (PMID 24358206, 2013).
tumor (65 papers, 2002 to 2025). "The interaction between THPO and the tumor immune microenvironment, particularly its association with M2 macrophages, underscores a critical aspect of its role in cancer biology." (PMID 41049174, 2025). "In paraneoplastic thrombocytosis, higher interleukin-6 production of the tumor modulates thrombopoietin production of the liver, which ultimately causes a significant increase in bone marrow platelet production." (PMID 33383764, 2020). "This association indicates that THPO might influence tumor growth and metastasis, potentially by modulating cellular mechanisms such as cell proliferation, apoptosis, and migration." (PMID 41049174, 2025). "In addition, the tumor-associated production of the granulocyte-macrophage colony stimulating factor or thrombopoietin mediated by IL-6 is considered to be responsible for the increase in the PLT observed in cancer patients." (PMID 29285316, 2017). "The inflammatory state and suppressive tumor microenvironment associated with large and metabolically active tumors can explain the potential impact on hematopoiesis and platelet count recovery, necessitating more frequent use of thrombopoietin agonist and stem cell boost for EMD patients." (PMID 38821914, 2024). "Second, although we observed correlations between THPO expression and M2-like macrophage infiltration, the direct immunomodulatory effects of THPO on the tumor microenvironment require mechanistic validation through dedicated functional assays." (PMID 41049174, 2025). "Mechanistically, THPO promoted epithelial–mesenchymal transition and showed a positive correlation with M2 macrophage infiltration, implicating it in tumor progression." (PMID 41049174, 2025). "PLT levels are usually lower in early tumour stages due to low tumour load, hypersplenism and other factors such as reduced production of thrombopoietin and increased capture of platelets by the spleen, where platelets are less affected by tumour factors." (PMID 39834808, 2024). "Tumor‐derived interleukin‐6 stimulates hepatic synthesis of thrombopoietin, resulting in increased platelet production." (PMID 38230764, 2024). "Tumor cells can secrete inflammatory mediators, thrombopoietin, and leukemia inhibitory factor, which promote the differentiation of megakaryocytes to platelets." (PMID 36033468, 2022). "According to previous reports, tumor cells secrete interleukin-6 (IL-6) to stimulate thrombopoietin production at the tumor site, which in turn promotes megakaryocytopoiesis and thrombopoiesis." (PMID 36330089, 2022). "Hepatic thrombopoietin synthesis that arises in response to tumour-derived IL-6 induces an increase in platelet counts, promoting tumour growth and producing a positive feedback loop." (PMID 36077635, 2022). "Tumor cells can increase the number of platelets in blood via thrombopoietin, IL-6 or leukemia inhibitory factor, and in turn, platelets facilitate tumor cell survival and escape from immune clearance mechanisms." (PMID 35958590, 2022). "THPO mRNA levels were significantly higher in tumor specimens than in LC tissues from the same patient (mean ± SEM: 3.48 ± 0.46 vs. 2.61 ± 0.40." (PMID 33673041, 2021). "The hepatocyte expression of THPO protein was evaluated by IHC in HCC and corresponding LC samples; THPO protein levels were much higher in tumor cells than in associated cirrhotic liver, (mean ± SEM H-score: 124.50 ± 9.31 vs. 76.40 ± 8.05)." (PMID 33673041, 2021). "Compared to control subjects, chromogranin A level was higher in the CgA+ group (p = 0.0086), thrombopoietin (p = 0.0040) and chromogranin B (p = 0.0070) in the CgA− group, while interleukin-6 was high in both tumor groups (p ≤ 0.0090)." (PMID 33383764, 2020). "Plasma interleukin-6, thrombopoietin, and serum chromogranin A and -B were measured; furthermore, tumor tissue was immunohistochemically stained for CgA+." (PMID 33383764, 2020). "Currently, it is believed that thrombopoietin is secreted by tumour cells, just as interleukin-6 is." (PMID 30824727, 2019).
tumor (continued). "Paraneoplastic thrombocytosis was driven by IL-6 and hepatic thrombopoietin, both of which stimulated tumor cell proliferation and migration; however, the mechanism is not clearly understood." (PMID 30630439, 2019). "The tumor cells can increase peripheral platelet count via thrombopoietin, IL-6 or leukemia inhibitory factor." (PMID 30103707, 2018). "Tumor-associated humoral factors and cytokines, including granulocyte colony-stimulating factor (G-CSF), granulocyte-macrophage colony-stimulating factor (GM-CSF), interleukin-1 (IL-1), and thrombopoietin (TPO), influence the formation of tumor-associated platelets." (PMID 39852571, 2025). "THPO was inversely related to tumor stemness indices—mRNAsi and EREG-mRNAsi." (PMID 41049174, 2025). "Furthermore, THPO expression correlated positively with tumor-infiltrating M2-polarized macrophages and other immunosuppressive cell subsets." (PMID 41049174, 2025). "The upregulation of THPO and its association with these pathways suggest that it may serve as a regulatory factor in the complex network of signals that promote EMT and tumor progression." (PMID 41049174, 2025). "Tumor-derived factors, such as thrombopoietin, stimulate platelet production in the bone marrow." (PMID 38993472, 2024). "Therefore, an increase in hemoglobin and hematocrit values in our patients with early EC can be explained by tumor-induced secretion of erythropoietin, similar to thrombopoietin." (PMID 36626395, 2023). "In addition, tumour cells can secrete substances such as inflammatory mediators, thrombopoietin and leukaemia inhibitory factor, which promote platelet activation 25-28." (PMID 37859820, 2023). "A direct effect of sunitinib on tumor proliferation may result in reduced levels of thrombopoietin and thereby lowering of the platelet count." (PMID 35698081, 2022). "In addition, cancer cells can release thrombopoietin and inflammatory mediators, which can promote platelet growth, in turn promoting tumor growth." (PMID 32026332, 2021). "The activated platelets facilitate tumor cell proliferation by secreting a number of angiogenic tumor growth factors, such as thrombopoietin (TPO), platelet factor 4 (PF4), transforming growth factor beta (TGFb), vascular endothelial growth factor (VEGF) and platelet-derived growth factor (PDGF)." (PMID 32867390, 2020). "Driving thisthrombosis may be tumour-derived thrombopoietin, and tumour- and platelet-derivedgrowth factors and microparticles." (PMID 19043612, 2008). "Correlation between platelet count and thrombopoietin levels was only significant in the CRC group (Spearman ρ: –0.24, p = 0.0332), whereas no (p = 0.8486) and marginal association (p = 0.0643) was found in the CRC + T2DM and in the two tumor groups combined, respectively." (PMID 35071777, 2022). "GSEA further revealed that THPO plays a crucial role in pathways promoting EMT, a key process in tumor metastasis." (PMID 41049174, 2025). "The increase in PLR with increasing stage is related, firstly, to the increased production of thrombopoietin (TPO) and IL-6 by tumor cells and, secondly, to the fact that tumor cells directly stimulate platelets." (PMID 39940871, 2025). "GSEA analysis revealed upregulation in pathways such as Notch, TGF-β, and both interferon responses in patients with high THPO expression, pointing to its role in EMT, a critical process in tumor metastasis." (PMID 41049174, 2025). "Five genes were subsequently selected by LASSO regression; CGB5, THPO, and PDGFRB were upregulated in the tumor tissue, while SLC10A2 and APOD were downregulated." (PMID 38228846, 2024). "In the HCC context, the increased THPO level appears to be a novel mediator capable of modifying the biology of malignant THPOR-positive hepatocytes, by triggering signaling pathways with tumor progression activities." (PMID 33673041, 2021).
tumor (continued). "A significant linear correlation emerged between THPO and VEGF-A transcripts in HCC and, at the protein level, THPO and THPOR were significantly correlated with VEGF-A in tumor tissues." (PMID 33673041, 2021). "This assumption is demonstrated by the mRNA and protein cross-inhibition between THPO and VEGF-A, which has been observed in hypoxic Huh7 and HepG2 cells to mimic in vivo tumor condition, upon cell transfection with VEGF-A-siRNA and THPO-siRNA." (PMID 33673041, 2021). "In the 3q27 band are found the THPO gene, involved in the cellular development process, and the BCL2 tumor suppressor gene." (PMID 27479010, 2016). "Tumor derived interleukin-6 increases hepatic thrombopoietin, which stimulates bone marrow megakaryocytes and platelet production of TGF-β1, which in turn activates the TGF-β1/smad proliferation pathway in tumor cells." (PMID 27502272, 2016). "For example, an Ad5 viral vector coexpressing human thrombopoietin (hTPO) and human NIS proteins in tumor cells (Ad-CMV-hTPO-T2A-hNIS) enhanced radioiodine uptake and prolonged radioiodine retention." (PMID 24926342, 2014). "Recombinant thrombopoietin (TPO) was used to expand MKs in the marrow and resulted in decreased skeletal lesion development after intracardiac tumor inoculation." (PMID 20684002, 2011). "Thrombopoietin (TPO), the major MK growth factor is required for MK proliferation and maturation and was used to expand MKs to determine their impact on tumor metastasis in vivo." (PMID 20684002, 2011). "Within the tumor microenvironment, PDGF may collaborate with thrombopoietin to enhance platelet production." (PMID 40837560, 2025). "Thrombopoietin is increased in dogs with carcinoma regardless of platelet count, but is likely only 1 component of a more complex pathophysiology in the tumor environment of carcinoma in dogs." (PMID 34881459, 2022). "THPO, in turn, by stabilizing HIF-1α, induces VEGF-A dependent autocrine/paracrine loops, acting on VEGFR-2 expressing tumor, or on non-tumor cells that may affect HCC development and progression." (PMID 33673041, 2021). "However, in light of the present findings, recreating hypoxic conditions could retrigger the deleterious THPO/VEGF-A positive feedback, favoring tumor growth." (PMID 33673041, 2021).